GSK3B (glycogen synthase kinase 3 beta)
Diseases named in the same sentence as GSK3B in open-access papers (continued):
Sharing a sentence is not in itself a finding about the gene and the disease.
tumor (continued). "Western blotting analysis revealed that tumor tissues formed from HOXA4-overexpressing cells displayed higher levels of HOXA4 and GSK3β and lower levels of β-catenin than did cells in the vector group." (PMID 29700285, 2018). "Immunostaining results showed that GSK-3β was repressed and β-Catenin was activated in miR-10a OE KGN-formed tumor." (PMID 30348959, 2018). "It is worthy to note that our current study of PSAT1 focused on GSK-3β, through which PSAT1 eventually enhanced the proliferation and metastasis of tumor cells." (PMID 29216929, 2017). "Celecoxib treatment also decreased the expression levels of Wnt pathway components and target genes, such as β-catenin, p-GSK-3β, MMP-2, Survivin, AXIN2, CYCLIN-D1 and C-MYC, and the CSC marker SOX-2 in the xenograft tumor tissues." (PMID 29383157, 2017). "They inhibit GSK-3β, leading to nuclear localization of β-catenin which binds its nuclear targets, such as TCF/LEF-1, and induces gene transactivation and tumor formation." (PMID 29379583, 2017). "AKT has pleiotropic oncogenic functions that include inhibition of multiple tumor suppressors, such as FOXO1/FOXO3A, Bad, p27, and GSK3β, and promotion of other oncogenic pathways, such as mTOR, p70S6K1, Rac, and survivin." (PMID 29088759, 2017). "Our results provide evidence that miR-302a synergistically increases the sensitivity of AML cells to VP-16 and demonstrate that miR-302a downregulates Rad52 to inhibit tumor growth and chemoresistance, in part via the AKT/Gsk-3β/β-catenin signaling cascade." (PMID 29088754, 2017). "Activation of CXCR2 mainly induced the PI3K/Akt/GSK-3β/Snail signaling pathway and the subsequent epithelial- mesenchymal transition (EMT) to promote tumor cell invasion and metastasis." (PMID 29312644, 2017). "Inhibition of GSK3β activity by treatment with each drug and the CLOVA cocktail was confirmed by the decreased level of pGSS641 in tumor cells, especially in satellite lesions, and the effect of CLOVA cocktail was strongest." (PMID 28423558, 2017). "Immunohistochemical analysis of the patients’ tumors suggested that the repurposed drugs inhibited GSK3β activity in the tumor cells, decreased expression of MIB-1 cell proliferation marker, and reduced invasion by the residual tumor cells." (PMID 28423558, 2017). "GSK3B phosphorylation is functionally inhibitory and anti-apoptotic, improving survival of UPR-stressed tumor cells (uniquely stressed by activated A2M)." (PMID 27323862, 2016). "Multiple key negative regulators, such as GSK-3β, APC, and ICAT, have been found to be suppressed in cancer, which contributes to the promotion of tumor progression through regulation of the oncogenic Wnt/β-catenin pathway." (PMID 26992223, 2016). "V2 isoform expression can inhibit tumor cell proliferation and metastasis through EMT modulation and by down-regulating EGFR signaling through ERK/GSK3β pathways." (PMID 27490467, 2016). "Klotho, an anti-aging and tumor suppressor protein expressed in renal tubular cells, inhibits PI3K/Akt/GSK3β/Snail signaling thus suppressing EMT, tumor invasion and migration." (PMID 26951092, 2016). "IGFBP6 knockdown activated the GSK3β/β-catenin/cyclin D1 pathway and enhanced CNE2 tumor cell growth and metastasis in a mouse model." (PMID 27623076, 2016). "Our data clearly demonstrated that WM130 decreased the phosphorylation of GSK3β (Ser9) in HCC cells and tumor xenografts, suggesting that WM130-induced β-catenin degradation was possibly mediated by the activation of GSK3β." (PMID 27783993, 2016). "We attempted to determine the in vivo relationship between GSK3β and phosphorylated EZH2 in human tumor samples by using antibodies against these phosphorylation sites, but the antibodies we generated did not work for immunohistochemical staining." (PMID 27494834, 2016).
tumor (continued). "We reported that PAX3-FOXO1 is phosphorylated at Ser201 by GSK3β and small molecule inhibitors of this enzyme not only reduce phosphorylation at this site but also attenuate ARMS tumor phenotypes." (PMID 27588498, 2016). "Inactivation of GSK-3β stimulates β-catenin, which in turn potentially regulates GSC differentiation and tumor progression via regulation of Notch pathway." (PMID 26755664, 2016). "Because some GSK-3β substrates are key proteins for promoting cell proliferation and survival, such as β-catenin and cyclin D16, GSK-3β is considered as a tumour suppressor." (PMID 26292722, 2015). "Our data differ from increased phosphorylation of rictor at S1235 by GSK-3β as reported in HEK293T cells and tumor cell lines." (PMID 25880554, 2015). "Western blot analyses of tumor tissues showed SMA significantly suppressed the phosphorylation of PI3K (p85), Akt, and GSK3β." (PMID 26544726, 2015). "The tumor-promoting effects of ILK, in part, is attributable to its ability to phosphorylate Ser473-Akt and GSK3β, as well as to induce the expression of the oncogenic transcription/translation factor Y-box binding protein 1 (YB-1)." (PMID 25821081, 2015). "Some studies support the idea of GSK3β and USF2 being tumor suppressive, other studies show a cancer promoting effect." (PMID 25741280, 2015). "Individually silencing sFRP4, GSK3β, or TLE1 increased the tumour sphere formation and enhanced the TOP flash/FOP flash activity of antagomir-942 cells." (PMID 25844602, 2015). "In the xenograft tumor tissues, SMA dose-dependently inhibited nuclear β-catenin along with reductions in GSK3β phosphorylation and increases in axin levels." (PMID 26544726, 2015). "The increased axin levels and GSK3β activity led to the phosphorylation and subsequent degradation of β-catenin in SMA-treated cancer cells (HT29) as well as tumor tissues (A549 xenograft tumor tissues)." (PMID 26544726, 2015). "Decrease phosphorylation of Akt (Ser473 and Thr308), GSK3β, FoxO3a and MAPK was also observed in treated groups by immunohistochemical analysis of tumor tissue sections." (PMID 25974307, 2015). "To go further, we transfected MCF7 cells with pCDNA3-HA-GSK-3β-S9A, that codifies a constitutively active form of GSK-3β, in order to enhance the level of active GSK-3β protein in the tumor cells." (PMID 25941117, 2015). "Our tumour spheroids were treated with glycogen synthase kinase-3 β (GSK-3β) inhibitors BIO and LiCl, which have previously been shown to specifically inhibit tumour cell invasion." (PMID 26244167, 2015). "Many components of the Wnt/β-catenin signaling pathway have critical functions in mammary gland development and tumor formation, yet the contribution of glycogen synthase kinase-3 (GSK-3α and GSK-3β) to mammopoiesis and oncogenesis is unclear." (PMID 25195860, 2015). "We found increased protein expression level of total GSK-3β and p-Ser9-GSK-3β in 46 of 60(76.7%)tumor tissues compared with their normal counterparts by western blotting." (PMID 25157753, 2014). "NSCLC patients with different clinical characteristics, such as sex, age, histological type and tumor-node-metastasis (TNM) stage, demonstrated similar levels of GSK3β." (PMID 24618715, 2014). "GSK3β, the key component that regulates canonical WNT/β-catenin and PI3K/Akt signaling pathways, is commonly considered a tumor suppressor in multiple cancers." (PMID 25937997, 2014). "Our study suggests that Matn2 functions as a tumor suppressor in hepatocarcinogenesis, and in this process activation of EGFR together with that of Erk1/2, as well as inactivation of GSK-3β, play strategic roles." (PMID 24691449, 2014). "Therefore, our results suggest that bufalin inhibits tumor growth and reduces pulmonary metastases in orthotopic transplantation tumor models of human HCC in nude mice, and the underlying mechanism is partly mediated by AKT/GSK3β/β-catenin/E-cadherin signaling pathways." (PMID 24581171, 2014).
tumor (continued). "The tumor growth inhibition of NVP-BEZ235 targeting NPC xenografts was dose-dependent, and the observed effect of the phosphorylation of AKT, GSK3β, S6K and 4E-BP1 correlated with the amount of compound presented in the tumor tissue." (PMID 23533654, 2013). "An increased therapeutic ratio can be accomplished by either tumor-specific sensitization (BRCA1 nuclear export and HR attenuation) or by neuron-specific radioprotection (GSK3β inhibition and NHEJ potentiation)." (PMID 23388100, 2013). "Accordingly, we extended our analysis by examining inactive form GSK3β and LCRMP-1 protein expression levels in tumor specimens from 142 NSCLC patients." (PMID 22363707, 2012). "Inhibition of PI3K activity (LY294002) in A431 tumor cells attenuated the TG2-induced activation of Akt and GSK-3β, and suppressed the increases in Snail, MMP-9, and cell motility." (PMID 21777419, 2011). "It has been reported that the activity of GSK-3β was required for Mcl-1 degradation, which is an essential mechanism for GSK-3β-induced apoptosis and contributes to GSK-3β-mediated tumor suppression and chemosensitization." (PMID 22046442, 2011). "Thirty-two primary tumor tissues obtained from patients diagnosed with GBM were studied using microarray and western blot analysis to measure GSK3β mRNA and protein levels." (PMID 19823589, 2009). "Interference with GSK3β activity by siRNA, the specific inhibitor SB216763, or lithium chloride (LiCl) induced tumor cell differentiation." (PMID 19823589, 2009). "Genes of this pathway up-regulated in CC tumor cells were JUN, MYC, FZD2, RAC1, GSK3B and CTNNB1, and a few others." (PMID 17822553, 2007). "ODC1 promotes tumor cell proliferation and mobility via the AKT/GSK3β/β‐catenin pathway." (PMID 40988561, 2026). "Immune infiltration analysis suggested that GSK3B and IDO1 may influence the tumour immune microenvironment." (PMID 42220063, 2026). "CDH17 promotes tumor growth through the Ras/Raf/MEK/ERK and β-catenin/GSK-3β signaling pathways." (PMID 41595482, 2026). "These high-STK38 cells may acquire the capacity to activate Hedgehog signaling through GSK3β and KIF7, thereby promoting the expansion of undifferentiated tumor subpopulations and enhancing tumor plasticity." (PMID 41540036, 2026). "Additionally, we found that corticosterone inhibits GSK3β activity, which led to the upregulation of key Notch signaling pathway members (NICD and HES1) in OC cells, thus facilitating tumor progression and metastasis." (PMID 41488655, 2025). "However, blocking AKT phosphorylation can down-regulate the expression of downstream GSK-3β and inhibit the expression of EMT-related genes such as Vimentin, Snail and β-catenin, thereby inhibiting tumor metastasis." (PMID 40265472, 2025). "For example, in more aggressive undifferentiated TC, GSK-3β activity is higher, which may further promote the phosphorylation of ADAR and TRIM47-mediated degradation, thereby exacerbating tumor progression." (PMID 40618019, 2025). "Complete loss of GSK3 causes intestinal defects, whereas individual deletion of GSK3α or GSK3β preserves normal intestinal structure and survival without tumor development." (PMID 41300341, 2025). "Here, western blot analysis showed that the expression of p-GSK3B and p-SMAD3 in 22RV1 cells and PC-3 tumor cells was significantly upregulated compared to that in RWPE-2 cells, suggesting that the EPHB1-GSK3B-SMAD3 signaling pathway was activated during PRAD development." (PMID 40548257, 2025). "Its downregulation in GSK-3β-OE cells suggests that GSK-3β may suppress inflammation, potentially creating an immune-suppressive niche that favors tumor survival and progression." (PMID 41321870, 2025). "Intriguingly, the expression of T334A 53BP1 in SB28 dramatically enhanced response to Olaparib-induced cell killing and tumor control without further effect on PARPi sensitivity with GSK3B inhibition." (PMID 41243969, 2025).
tumor (continued). "Additionally, genipin decreases tumor cells’ resistance by lowering the expression of EGF, EGFR, PKB, and GSK-3β." (PMID 40656954, 2025). "They found that circ-GSK3B acts as a tumor suppressor in LUAD by increasing and activating GSK3B." (PMID 40070571, 2025). "Despite the importance of the GSK3β/STAT3 axis in this process, we observed that inhibition of GSK3β or STAT3 signaling does not generate valuable survival benefits in GBM tumor–bearing mice." (PMID 40131864, 2025). "The observed differences in GSK3B expression likely represent an adaptive response to tumor heterogeneity rather than a determinant of drug sensitivity." (PMID 41019981, 2025). "Additionally, we found a significant upregulation of p-β-catenin and GSK-3β, and a significant downregulation of CELSR2, β-catenin, p-GSK-3β and cyclinD1 in the CELSR2-KD group compared to the control group in the tumor nodule, as assessed by RT-qPCR." (PMID 41184253, 2025). "Further mechanism studies showed that LRRC1 enhances PDK1 stability by promoting its deubiquitination via USP7, thereby increasing AKT1 phosphorylation levels and activating the AKT/GSK3β/β-catenin/VEGFA signaling pathway, ultimately accelerating tumor angiogenesis in HCC." (PMID 41369408, 2025). "We demonstrated that inhibition of tumor-macrophage symbiosis via blockade of integrin αv combined or not combined with GSK3β or STAT3 inhibition promotes the infiltration and activation of T cells, especially CD8+ T cells, in the GBM TME." (PMID 40131864, 2025). "In tumor cells, LDHC contributes to metabolic reprogramming by driving aerobic glycolysis and promotes tumor cell invasion, migration, and proliferation through activation of the PI3K/Akt/GSK-3B signaling pathway." (PMID 40108668, 2025). "FMRP interacts with both GSK3β and CTNNB1, MSI1 represses APC and enhances Wnt signaling in epithelial progenitors, while MEX3A stabilizes LGR5 and represses DKK1, thereby promoting stemness and tumor progression." (PMID 41516083, 2025). "Then, we proved that inhibiting the expression of GSK3B could suppress the phosphorylation of β-catenin and promote the transcription of PROX1, thus leading to tumor lymphangiogenesis." (PMID 39866224, 2025). "Active GSK-3β also results in the phosphorylation, followed by the degradation, of β-catenin, while GSK-3β inactivation by Akt increases the stability of both β-catenin and Snail, which play a crucial role in tumor progression." (PMID 38786044, 2024). "All these PI3K isoforms promote tumor cell survival, proliferation and metastasis by regulating different processes including tumor cell metabolism, angiogenesis and by modulating the TME and immunity, mainly via the activation of the AKT/mTOR and the GSK3β/beta-catenin pathways." (PMID 38420122, 2024). "PDAC with low Ser9 phosphorylation of GSK‐3β inflicts a negative prognosis owing to sustained tumor‐promoting signals." (PMID 39632551, 2024). "Thus, we examined the glycogen synthesis conditions in the liver and found that only tumor-bearing mice treated with a PI3K inhibitor exhibited significantly high glycogen levels, accompanied by elevated expression of p-GSK3β." (PMID 38755637, 2024). "In tumor-bearing mice, GSK3β inhibition did not ameliorate tumor-infiltrating CD8+ T cells and antitumor treatment efficacy, suggesting that LC has a GSK-independent antitumor function." (PMID 38263463, 2024). "Therefore, these two pathways can interact with the Wnt/β-catenin signalling pathway through GSK-3β, upregulate the expression level of snail, reduce the expression of E-cadherin, and theoretically promote the occurrence of EMT and tumour metastasis." (PMID 38317072, 2024). "GSK-3β can recognize and phosphorylate β-catenin, generating a site that β-TrCP E3 Ub ligase can bind to, triggering the ubiquitination and degradation of β-catenin, thereby eliminating its EMT-promoting effect and reducing the metastasis of tumor cells." (PMID 37847340, 2024).
tumor (continued). "Ferroptosis induced by GSK-3β overexpression can be attenuated by Nrf2, suggesting that targeting the GSK-3β/Nrf2 axis may hold promise for inhibiting tumor growth." (PMID 38481820, 2024). "Mechanistically, we propose a functional model wherein DNMT1-remodeled genome-wide DNA hypomethylation patterns regulate oral malignant transformation and tumor growth, through signal collaborations involving PI3K-AKT, CDK2-Rb and GSK3β-mediated glycogen metabolism." (PMID 38755637, 2024). "Therefore, SPO and GSK3β are probably involved in downregulation or degradation of GLI3 and promotes tumor aggressiveness in PCa tissues." (PMID 38370352, 2024). "Consistent with reduced expression of NLRP12 in WT tumor, there was increased activation of β-catenin accompanied by higher phosphorylation of GSK3β in tumor tissue compared with adjacent nontumor tissue of WT mice." (PMID 37581937, 2023). "The triple-drug combination significantly (p < 0.0001) reduced the gene expression levels of VEGF, VEGFR, PI3K, PDK1, AKT1, mTOR and GSK3β while it significantly (p < 0.0001) enhanced the expression of PTEN, when compared with the tumor-control (TC) and other treatment groups." (PMID 37025487, 2023). "Additionally, Western blot analysis of tumor tissues demonstrated that theasinensin A plus nimotuzumab resulted in a greater suppression of p-EGFR, p-ERK1/2, p-STAT3 and p-GSK3β." (PMID 37762316, 2023). "Collectively, TIPE2 may act as a tumor suppressor in EOC through PTEN activation and PI3K/Akt signal inactivation, which in turn leads to GSK3β dephosphorylation." (PMID 36801818, 2023). "We have also identified that NDRG1 is downstream of TGFβ-induced GSK3β, and our results suggest that the role of NDRG1 in tumor promotion could be attributed to the modulation of NF-κB." (PMID 36594086, 2023). "GSK3β most likely functions as a tumor suppressor in PC3 and as a tumor promoter in DU145, which may explain why strictinin decreases the phosphorylation of GSK3β (active) in PC3 cells and increases the phosphorylation of GSK3β (inactive) in DU145 cells." (PMID 38213538, 2023). "Notably, silencing MYH9 significantly attenuates ACTN1's tumor-promoting effects, supporting the notion that ACTN1 drives HNSCC tumorigenesis primarily by boosting MYH9-dependent GSK-3β degradation." (PMID 38057867, 2023). "Given that TGFβ1 was found to activate GSK3β (p-GSK3β Tyr216) in MCF10A breast cells and human fibroblasts 36,37, we questioned whether staining of this active form in TNBC tumor tissue, could correlate with NDRG1 and p-NDRG1 staining." (PMID 36594086, 2023). "Our study found that GSK3B binds to ATP probe in two of four samples from tumor tissues of GAC with LNM, but not in the control group." (PMID 36520032, 2023). "Thus, PPP1R14C promotes the aggressiveness, tumour growth, and metastasis of TNBC cells in vitro and in vivo by sustaining inactive GSK3β." (PMID 35090098, 2022). "Furthermore, quercetin decreased the protein levels of p-GSK-3β (Ser 9), β-catenin and ZEB1 in tumor tissue." (PMID 36386155, 2022). "In the tumor immune microenvironment, DDAH1 overexpression inhibited the Wnt/GSK-3β signaling, which may enhance the recruitment of T cells." (PMID 35578598, 2022). "KPNA2 promotes the phosphorylation of AKT and GSK-3β in tumour cells without altering the expression of total AKT or GSK3β." (PMID 36578083, 2022). "Taken together, this study reported a new regulatory axis linc00958/miR-185-5p/RSF-1 in cisplatin resistance and tube formation in CC via AKT1/GSK3β/VEGFA pathway and knockdown of linc00958 could also inhibit the tumor growth and angiogenesis." (PMID 36056431, 2022). "Additionally, we inspected the p-Akt (Ser473), p-GSK-3β(Ser9), Snail, E-cadherin, N-cadherin and Cyclin D1 contents in HCC tumor tissues using IHC." (PMID 33762939, 2021). "However, for the KRASG12C tumor, LINCS analysis returned different drugs (NES < −3.6, P < 0.04), inhibitors of HSP70, GSK3β, and KRAS signal transducers BRAF and RAF1." (PMID 33712615, 2021).